CX3CR1 (C-X3-C motif chemokine receptor 1)
Diseases named in the same sentence as CX3CR1 in open-access papers (continued):
Sharing a sentence is not in itself a finding about the gene and the disease.
tumor (continued). "The fractalkine axis (CX3CL1/CX3CR1) is a key factor in the interaction between tumor cells and growth-supporting cells in the TME." (PMID 39594776, 2024). "CX3CR1+ macrophages were reported to have both anti- or pro-tumor effects in malignant tumors, and therefore, their functions are controversial." (PMID 38658971, 2024). "Further studies are warranted to explore the anti-tumor effects of the CX3CR1 antagonist in CLL as well as other malignancies." (PMID 39594776, 2024). "The functional domain–deleted models showed a significant reduction in the recruitment of CX3CR1+ cells into the TME compared with MOC2CX3CL1 tumor models." (PMID 38775151, 2024). "Conversely, the CX3CL1/CX3CR1 axis has been shown to promote cancer cell proliferation, migration, and invasion, along with recruiting pro-tumor immune cells." (PMID 38775151, 2024). "The interaction between CX3CL1 and CX3CR1 regulates the adhesion of immune cells to tumor cells, influencing the metastatic potential of cancer." (PMID 38456941, 2024). "They support this suggestion by highlighting the fact that tumor grade was also a predictor of patient survival in their tumor analysis, with CX3CR1 expression retaining prognostic value when adjusted for tumor grade as well." (PMID 38339310, 2024). "More directly, in vivo studies have shown that co-expression of CX3CL1 and CX3CR1 led to a more malignant tumor phenotype with increased microglia/macrophage infiltration and microvessel density, and shorter overall survival." (PMID 38893093, 2024). "To confirm the role of INHBA on the CX3CR1+ macrophages NR5A1+ tumor cells interaction axis, we treated primary cells and PitNET cell lines with INHBA." (PMID 38658971, 2024). "We found that CX3CR1+ macrophages regulated NR5A1+ tumor cells through regulation of signaling receptor pathway and TGF-β stimulus." (PMID 38658971, 2024). "We have shown the different effects of different tumor spheroids on the surface level of CX3CR1 in pNK cells." (PMID 39457710, 2024). "Intriguingly, NR4A1-dependent LY6Clo NCMs migrate toward tumor colonies using the CX3CR1/CX3CL1 axis, where they have been suggested to mediate tumor lysis." (PMID 39545417, 2024). "The MDSC (CD11b+Gr1+) were the predominant CD11b+ population in the isotype-treated tumor bearing mice but were reduced in all three immunotherapy treatment groups of anti-PD-1, anti CX3CR1, and anti-PD-1 + anti CX3CR1." (PMID 37771579, 2023). "CX3CR1 cell depletion attenuates tumor progression following radiation and sensitizes the tumor to S-phase-specific chemotherapy." (PMID 38001732, 2023). "Previous studies suggest a role of CX3CR1 in tumor metastasis by promoting angiogenic macrophage survival and angiogenesis in the tumor microenvironment." (PMID 36900266, 2023). "iFGFR1‐induced CX3CL1 enhanced the migration of macrophages during the initial stage of tumor formation and blocking CX3CR1 significantly decreased the recruitment of macrophages in MMTV‐iFGFR1 mice." (PMID 36794651, 2023). "We observed slower tumor growth and increased survival in the anti-CX3CR1 + anti-PD-1 combination group compared to anti-PD-1 alone." (PMID 37771579, 2023). "It has been shown that higher expression of CX3CR1 in macrophages correlates with higher metastasizing potential and poorer clinical prognosis in tumor patients." (PMID 36900266, 2023). "Tumor cells which express CX3CL1 can induce the invasion and metastasis of CX3CR1-positive tumor cells." (PMID 37770496, 2023). "In Nf1 optic gliomas, TAMs are mostly CD11bhigh CD45low, and in mouse models with downregulated CX3CR1 expression, yet exhibit delayed tumor growth." (PMID 37700840, 2023). "Using a Boyden chamber-based migration assay, we found that CT26 tumor cells pre-treated with CX3CR1 mAb had reduced migration towards a CX3CL1 gradient." (PMID 37771579, 2023).
tumor (continued). "Emerging studies also suggest CX3CR1 as a marker of stem-like tumor cells and cells with relatively higher CX3CR1 expression show transcriptomic profiles enriched in pathways regulating pluripotency." (PMID 37770496, 2023). "The CX3CR1 monoclonal antibody can target both tumor and myeloid cells; inhibit tumor signals that recruit myeloid populations and inhibit immune-suppressive pathways regulated through this axis." (PMID 37771579, 2023). "Both CD45+CD11b+ and CD45+CD3+ populations in the tumor had higher CX3CR1 expression than their corresponding populations in the spleen." (PMID 37771579, 2023). "To investigate associations between CX3CR1 expression in OSCC, we first analysed levels of CX3CR1 mRNA expression in normal and tumour tissue." (PMID 37082943, 2023). "CXCR1 and CX3CR1 expression levels were significantly correlated with tumor purity and the infiltrating levels of macrophages and NKT in LUAD." (PMID 37770496, 2023). "Previous studies by our laboratory demonstrated that nMo phagocytize tumor antigens via CX3CR1 and subsequently recruit anti-tumoral natural killer cells, resulting in tumor killing." (PMID 37426658, 2023). "Collectively, these findings suggest that circulating clonally expanded T cells early after the initiation of chemo-immunotherapy overexpress CX3CR1, and contain repertoires of tumor-infiltrating T cells." (PMID 37009132, 2023). "Further investigation is necessary to elucidate the role of CX3CR1+CD4+ T cells in tumor immune response." (PMID 37509302, 2023). "Data from the GSE13601 microarray showed that, compared with the non‐tumour tissues, the mRNA expression of CX3CR1 was significantly downregulated in the tumour tissues (p < 0.01)." (PMID 37082943, 2023). "Secretion of soluble CX3CL1 can be part of a feedback loop to maintain a CX3CR1 driven immune-suppressive signaling program in the tumor." (PMID 37771579, 2023). "We observe higher survival and response in the syngeneic immunocompetent CT26 tumor model when anti-CX3CR1 is combined with anti-PD-1." (PMID 37771579, 2023). "CX3CL1 secreted in the tumor microenvironment serves as a chemoattractant playing a critical role in metastasis of CX3CR1 expressing cancer cells." (PMID 37771579, 2023). "We have recently shown that successful ICI therapy induces an expansion of the peripheral CX3CR1+ CD8+ T-cell subset that includes an enriched repertoire of tumor-specific and tumor-infiltrating CD8+ T cells in preclinical models." (PMID 37009132, 2023). "TAMs in the CT26 tumor express CX3CR1, and within the TAM subsets, M2 macrophages had higher CX3CR1 expression than M1 macrophages." (PMID 37771579, 2023). "To test this, we pre-treated CT26 tumor cells with 10 μg/ml of the CX3CR1 mAb followed by addition of CX3CL1 recombinant protein." (PMID 37771579, 2023). "CX3CL1/CX3CR1 signaling is constantly activated in the process of monocyte recruitment and subsequent differentiation to TAMs in the tumor niche." (PMID 37968706, 2023). "The CX3CL1-CX3CR1 axis has been shown to contribute to migration of tumor cells expressing CX3CR1 and promote metastasis." (PMID 37771579, 2023). "CX3CL1 is another member of the chemokine CXC subfamily, which can bind to CX3CR1 that is highly expressed on macrophages, and increase the accumulation of macrophages in tumor tissues." (PMID 36794651, 2023). "Combination anti-PD-1 + anti CX3CR1 treatment led to a significantly lower percentage of CD45+CD11b+ myeloid cells in the tumor compared to isotype." (PMID 37771579, 2023). "Collectively, these findings highlight the potential utility of T-cell CX3CR1 expression as a dynamic blood-based biomarker during the early course of chemo-immunotherapy and a marker to identify frequent circulating tumor-infiltrating lymphocyte repertoires." (PMID 37009132, 2023).
tumor (continued). "CXCL8 was a well-known chemokine involved in tumorigenesis, tumor progression and immune suppression, and CX3CR1 was regarded as a novel cancer targeted therapeutic strategy due to its immune activation capacity." (PMID 37064084, 2023). "Our previous studies also showed that effector CD8+ T cells need CX3CR1 for their accumulation at tumor sites." (PMID 36656137, 2023). "Survivors of single agent anti-PD-1 and combined anti CX3CR1 + anti-PD-1 had 100% percent survival when re-challenged with CT26 while control mice succumbed to the tumor, confirming immunological memory after the antibody treatments." (PMID 37771579, 2023). "Previous studies have shown that NLRP3 inhibition reduces MDSC infiltration into the tumor suggesting an additional mechanism for how CX3CR1 mAb blockade can reduce tumor immune evasion." (PMID 37771579, 2023). "CX3CR1 facilitates macrophage survival, leading to enhanced angiogenesis and metastasis of tumor cells." (PMID 37770496, 2023). "Our results show that the response to PD-1 mAb + CX3CR1 immunotherapy is characterized by a remodeling of the myeloid compartments in the tumor with the combination treatment skewing the myeloid populations towards fewer MDSC and more mature macrophages." (PMID 37771579, 2023). "CX3CL1 upregulates ICAM‐1 expression through the proposed CX3CR1/PLCβ/PKCα/s‐Src/AP‐1 signalling pathway and subsequently promotes tumour metastasis." (PMID 37082943, 2023). "The CX3CR1 monoclonal antibody reduces migration of tumor cells and decreases secretion of immune suppressive soluble mediators by tumor cells." (PMID 37771579, 2023). "CXCR3 and CX3CR1 are mainly responsible for infiltrating tumour-inhibitory lymphocytes into the tumour microenvironment, further confirming the results of immune cell infiltration." (PMID 37880315, 2023). "Our study reported that CXCR1 and CX3CR1 expressions were significantly negatively correlated with tumor purity whereas significantly positively correlated with infiltrating levels of macrophage in LUAD, especially M2 macrophages." (PMID 37770496, 2023). "We confirmed that a high percentage of M-MDSC in the CT26 tumor express CX3CR1, consistent with previous studies." (PMID 37771579, 2023). "Typically, LAG-3 and PD-1 expressions were greater in the tumor, while CX3CR1, CXCR3, and CD27 expressions were lower compared to the PB levels." (PMID 35003893, 2022). "It is supposed that CX3CR1 plays a role in anti-tumor immune responses via the recruitment and activation of effector T lymphocytes." (PMID 35625386, 2022). "On the contrary, in the low-risk group, the expressions of IL3RA, CX3CR1, ARRB1, LIFR, and VIPR1 were higher than those in the high-risk group, which signified that they have a tumor suppressor effect." (PMID 35833114, 2022). "Confocal imaging of the MC38-bearing liver lobes showed that CX3CR1+ cells surrounded some micrometastases near the PV in the liver on the third day after tumor cell injection, suggesting a close relationship between CX3CR1+ cells and micrometastasis." (PMID 35910800, 2022). "We found that CX3CR1 was highly expressed in the tumor and peripheral blood in group 11 and group 10, respectively." (PMID 36397015, 2022). "Targeting CX3CR1 delays the egress of circulating tumor cells from the blood circulation, induces cancer cell apoptosis, and reduces metastasis." (PMID 35754051, 2022). "The CX3CR1-knockdown tumor cells or transgenic mice will be used in the intrasplenic injection model to explore metastasis ability of CX3CR1." (PMID 35478937, 2022). "To analyze the mechanism by which CX3CL1 and CX3CR1 regulate liver metastasis, we first assessed CX3CR1 expression in tumor cell lines." (PMID 35478937, 2022). "In this model, we identified two populations, CD62L− CX3CR1+ and CD62L− CX3CR1−, in the primary tumor, ascites, and metastases." (PMID 36077756, 2022).
tumor (continued). "In our analysis, NEIL3 expression was positively correlated with pro-tumour chemokine receptors, such as CCR1, to some extent, but negatively correlated with anti-tumour receptors, such as CX3CR1, across cancers." (PMID 36612106, 2022). "The CXCR3 and CX3CR1 are mainly responsible for the tumor-suppressive lymphocytic infiltration into the tumor micromilieu." (PMID 35517862, 2022). "Tumor-associated macrophages (TAMs) crosstalk with LC cells via the C-C chemokine receptor type-2 (CCR2) and CX3C chemokine receptor 1 (CX3CR1)." (PMID 36618350, 2022). "Here, we defined a recruitment coefficient σ as σ = (GFP volume) / (tumor volume) to quantify the ability of colorectal cells to recruit CX3CR1+CCR2+ macrophages per unit tumor volume." (PMID 35910800, 2022). "The volume of CX3CR1+ cells around each tumor metastasis distributed in the PV was 14 times larger than that in the hepatic lobule." (PMID 35910800, 2022). "As PD-L1 expression in tumours has been described to augment the expression of other immunosuppressive biomarkers such as CX3CR1 at the local tumour microenvironment, we also quantified the double expression of PD-L1 and CX3CR1 after SFRE treatment." (PMID 36439419, 2022). "Tumor vaccine greatly boosted CX3CR1+ subset in TDLN, especially for Tgfbr2−/− cells, leading to significantly increased accumulation of this effector subset in the tumors." (PMID 36229613, 2022). "Since this cell population also expresses CX3CR1, migration of bone marrow-derived cells from tumor-bearing Ccr2+/RFP/Cx3cr1+/GFP mice to soluble CX3CL1 was assessed." (PMID 36685592, 2022). "Reduced HLADR and CD86 are features of immunosuppressive monocytes in cancer, while loss of CX3CR1/CX3CL1 signalling in monocytes and TME can accelerate murine tumour growth." (PMID 36589727, 2022). "CX3CR1+ memory T cell is an effector memory phenotype and has unique abilities in tumor therapy including withstanding the toxicity of chemotherapy and proliferating when using chemoimmunotherapy." (PMID 35528178, 2022). "In another study, chemokine receptor CX3CR1 showed a role in angiogenic macrophage survival in the tumor microenvironment contributing to tumor metastasis." (PMID 36497286, 2022). "Pearson correlation analysis further showed that OPN was positively associated with M2 macrophage markers (CD163, VSIG4, MS4A4A, CX3CR1, and MRC1) and tumor-associated macrophage (TAM) markers (CCL2, CD68, and IL10)." (PMID 35669197, 2022). "The mir-561-5p/chemokine (C-X3-C motif) ligand 1 (CX3CL1)/natural killer (NK) cell axis drives HCC metastases and shows that CX3CR1+ NK cells act as the strong anti-tumor therapeutic factors." (PMID 35215154, 2022). "Taken together, these results suggest that bone marrow-derived CCR2+/CX3CR1+ cells from naïve and tumor-bearing animals migrate to CCL2 and CCL7, in a CCR2-dependent manner." (PMID 36685592, 2022). "The high frequency of tumor-specific CD8+ T cells in the CX3CR1+ subset before and during ICI treatment is suggestive that heterogeneous tumor-infiltrating CD8+ T cells are also enriched in the CX3CR1+ subset." (PMID 33658501, 2021). "Elevated expression of CXCR4 and CX3CR1 chemokine receptors and matrix metalloprotease proteins on ‘helped’ CTLs augment their extravasation and infiltration into the tumor." (PMID 34012451, 2021). "On the other hand, DCs constitutively express CX3CR1 34, so it would be very interesting to evaluate in a carcinogenesis model, if immature DCs can be recruited into the tumor by exogenous CX3CL1." (PMID 33391453, 2021). "Other receptors such as CCR5, CCR6, CXCR2 and CX3CR1 were mostly identified for their expression and function in immune cells from the tumor microenvironment." (PMID 35008294, 2021). "This would confirm the assumption of CX3CL1 as a trigger for the activation of effector cells and promotor for stronger adhesion of leucocytes to CX3CR1-positive tumor cells as postulated before." (PMID 34070094, 2021).
tumor (continued). "Using mouse glioma models which enable the differentiation of genetically labelled MDM (Ccr2 RFP) and MG (Cx3cr1 GFP), they showed that microglia associated tumor cells increase tumor cell phagocytosis in response to CD47/SIRPA axis inhibition." (PMID 34168976, 2021). "Here, we reported that MK3 expression was positively correlated with the majority of chemokines and chemokine receptors, such as CCL, CXCL12, CCR, CXCR2, CXCR4, and CX3CR1, which play pro-tumor roles." (PMID 34938665, 2021). "The correlations between CX3CR1 and tumor-infiltrating immune cells were estimated by Tumor IMmune Estimation Resource database (TIMER) and CIBERSORT analysis." (PMID 35140706, 2021). "As such, targeting the fractalkine: CX3CR1 pathway with therapeutic intent to reposition crucial T and NK cells from omentum to tumour is of great interest in OAC." (PMID 35008227, 2021). "There was no significantly enhanced formation of lung metastases or DTC accumulation in the bone marrow in MDA-MB-453CX3CL1 mice, even though the CX3CL1 receptor CX3CR1 was strongly upregulated in MDA-MB-453 tumor cells." (PMID 34070094, 2021). "It has been reported that chemokine CX3CL1 can regulate various tumours by binding to its unique receptor CX3CR1." (PMID 33191645, 2021). "Selective deletion of Nhe1 in Cx3cr1+Nhe1 KO mice increased anti-tumor immunity and sensitivity to TMZ plus anti-PD-1 combinatorial therapy." (PMID 33391535, 2021). "In an aggressive B16F10 murine melanoma model, IL-21 secretion stimulated by CD4+ TH cells drives CD8+ T cell differentiation towards CX3CR1+ cytotoxic effector phenotype and anti-tumor activity." (PMID 34012451, 2021). "Similar CX3CR1 profiles on the different immune cells were found on the tumor infiltrating immune cells." (PMID 34070094, 2021). "This provides further evidence for using CX3CR1 antagonists to reduce NK cell migration to fat and boost NK cell movement to the tumour." (PMID 35008227, 2021). "The differential expression of CX3CR1 between tumor and adjacent normal tissues was analyzed using the DiffExp module of the TIMER database." (PMID 35140706, 2021). "The increase of circulating CX3CR1+ CD8+ T cells was also observed in MC38 tumor-bearing mice treated with anti-PD-L1 therapy alone with improved tumor control and survival." (PMID 33658501, 2021). "To this end, we performed TCR sequencing on isolated CD8+ TILs and splenic CD27lo CX3CR1−, CD27hi CX3CR1−, and CX3CR1+ CD8+ T cells from MC38 tumor-bearing mice treated with combined anti-CTLA-4/PD-L1 therapy." (PMID 33658501, 2021). "It targets upregulation of CCL-2/CCR-2 and CXC3CL-1/CX3CR-1 axis in macrophage-tumour cell crosstalk." (PMID 34336101, 2021). "Consistently, the CX3CR1+CD8+ T cells of highly cytotoxic potential shared TCR clonotypes with tumour infiltrating CD8+ T cells, which are responsible for recognising antigens." (PMID 33531485, 2021). "In the oxygen-deprived TME, hypoxia-driven HIF can induce the recruitment of CX3CR1-expressing MDSCs by activating the transcription of CCL26 in tumor cells." (PMID 33422072, 2021). "Histological analysis showed reduced levels of phosphorylated PI3K and AKT, and decreased levels of MMP-2 in CX3CR1-KD groups than those in control groups, indicating downregulation of the aggressive propensity of tumor cells conferred by CX3CR1-KD treatments." (PMID 33754027, 2021). "Of note, a specific CX3CR1 defective polymorphism (V249I) correlates with increased patient survival in patients with GBM and LGG, stressing its important role in tumor maintenance." (PMID 35008294, 2021). "The CX3CL1/CX3CR1 axis has both tumor-promoting and suppressive effects in cancer progression, resulting in either favorable or unfavorable prognosis depending on the cancer types." (PMID 31991604, 2020). "In this cohort, measurement of tumour volume confirmed that tumours were significantly smaller in the Cx3cr1‐Rheb1Δ/Δ compared to Rheb1fl/fl mice." (PMID 32567735, 2020).